CD28 (CD28 molecule)
Diseases named in the same sentence as CD28 in open-access papers (continued):
Sharing a sentence is not in itself a finding about the gene and the disease.
breast cancer (continued). "In both MMTV-PyVT and MCaP0008 breast cancer models, tiMDSC (Gr1+F4/80−) inhibited T cell proliferation induced by anti-CD3/CD28 monoclonal antibodies; however, TAM (Gr1−F4/80+) was much more potent than tiMDSC in suppressing T cell proliferation." (PMID 28903332, 2017). "PBMCs from breast cancer patients were stimulated overnight through the T-cell receptor with anti-CD3 and anti-CD28 antibodies and interrogated for intracellular TNF-α synthesis by multiparameter flow cytometry." (PMID 26207636, 2015). "In order to further elucidate the functional properties of monocytes from breast cancer patients, freshly isolated monocytes were co-cultured with CD3/CD28 activated naïve CD4+ T cells in an allogeneic T cell suppression assay." (PMID 25992611, 2015). "We then applied our method to reconstruct signaling downstream of CD3, CD28 and LFA-1 in CD4 T-cells, as well as signal transduction in the ErbB pathway in breast cancer cells." (PMID 23935958, 2013). "We studied CD28 and CD3-ζ expression in sentinel node biopsies (SNB) from breast cancer patients to analyze tumor-related changes in T cell activity." (PMID 15613231, 2004). "Several studies document decreased CD28 and CD3-ζ expression in peripheral blood from breast cancer patients in comparison to healthy individuals." (PMID 15613231, 2004). "CD28 expression was studied in CD4+ and CD8+ T-lymphocyte subsets and compared with CD3-ζ expression in sentinel node biopsies from breast cancer patients." (PMID 15613231, 2004). "In the present study, the down-regulation of CD28 and CD3-ζ clearly seems to be more accentuated in sentinel node biopsies than otherwise described in breast cancer patients." (PMID 15613231, 2004). "The present data on decreased expression of CD28 and CD3-ζ in sentinel lymph nodes confirm that breast cancer has an impact on local immunoreactivity." (PMID 15613231, 2004). "CAR-NK-92 cells based on CD28-CD3ζ signaling domain have anti-tumor cytotoxicity targeting EpCAM and ErB2 breast cancer cells, EGFR on glioblastoma cells and breast cancer brain metastases, CD19 on B-cell malignancies, CS1 on multiple myeloma cells, and CD33 on acute myeloid leukemia cells." (PMID 39633491, 2024). "Risk score also predicted expression of several immune checkpoints, including PD1, PDL1, PDL2, TIM3, CD28, ICOS, IL2RB, and 41BB, in TNBC patients, and its predictive value in these patients was similar to that observed in the overall breast cancer patient cohort." (PMID 32756008, 2020). "CD3 on CD28+ DN (CD4-CD8-) (P = 0.022, OR = 0.957, 95%CI = 0.922~0.993) and CD28 on activated Treg (P = 0.022, OR = 0.964, 95%CI = 0.935~0.995) had a negative causal relationship with breast cancer." (PMID 39418291, 2024). "In the present study, we demonstrated that PD-L1 expression on breast cancer cells was significantly downregulated by the overexpression of NDRG2, leading to the prevention of tumor cell-induced interference of splenic T cell proliferation stimulated with a combination of anti-CD3/CD28 antibodies." (PMID 34885221, 2021). "To identify factors that can induce CD177 expression on Treg cells, we purified human PB Treg cells or CD4 Tconv cells from breast cancer patients, or splenic Treg cells or CD4 Tconv from MC38 tumor-bearing mice, either non-stimulated (ns) or treated with anti-CD3/CD28 and IL-2." (PMID 34599187, 2021). "For example, within the top highly expressed genes in claudin-low tumors versus all others, there are several wound response-related genes (i.e., CD28, CD52) that are not expressed by the breast cancer cell lines, potentially due to significant immune or stromal cell content in the tumor." (PMID 20813035, 2010).
lymphoma (47 papers, 2007 to 2025). A malignant (clonal) proliferation of B- lymphocytes or T- lymphocytes which involves the lymph nodes, bone marrow and/or extranodal sites. "Aberrant expression of extracellular HSPs in CD3/CD28-activated T cells was also associated with lymphoma patients." (PMID 36359267, 2022). "Recurrent activating mutations in CD28 and CD28-CTLA-4 fusion proteins have been identified in T-cell leukemias and lymphomas, and these increase the ligands’ affinity and amplifying costimulatory signals that promote tumor immune escape." (PMID 40723175, 2025). "Here, we apply biophysical methods to characterize the structure and dynamic properties of the CD28 CAR hinge (CD28H) used in an FDA-approved CD19 CAR for the treatment of B-lineage leukemia/lymphoma." (PMID 39217198, 2024). "Studies have demonstrated that combining ICIs with CAR T cells or using CD19-CAR T cells engineered to express a PD-1/CD28 chimeric-switch receptor can significantly reduce tumor growth in PD-L1 positive lymphoma cells." (PMID 39328551, 2024). "In contrast, T cells of myeloma patients were less responsive to CD3/CD28 stimulation compared to lymphoma patients." (PMID 37187728, 2023). "The NCT02050347 trial tests donor CD19/CD28 chimeric receptor T cells in leukemia and lymphoma patients with residual disease at transplantation or post-transplant evidence of MRD positivity (or relapse)." (PMID 36983151, 2023). "Clinically, superior expansion and longer persistence were observed when CD19-directed second (CD28 costimulatory domain)- and third-generation (CD28 and 4-1BB) CARTs were simultaneously administered to lymphoma patients." (PMID 37481608, 2023). "In general, myeloma patients showed a reduced T cell activation via CD3/CD28 compared to lymphoma patients, especially for IFN- and TNF-producing T cells." (PMID 37187728, 2023). "It appears that T cells from lymphoma patients have a higher CD8+ T cell degranulation response when stimulated with allogeneic DCs than when stimulated with anti-CD3/CD28." (PMID 36359267, 2022). "Although T cells expressing CARs with either a 4-1BB or CD28 costimulatory domain have demonstrated similar antitumor activity, particularly against lymphomas, T cells expressing CD28-costimulated CARs display higher cytokine production but lower persistence." (PMID 36123710, 2022). "With specific regards to anti-CD19 CAR-T cell constructs, we focused on lymphoma to explore the difference of hematological toxicity between CD28 and 41BB, as two main co-stimulatory molecules in CAR-T therapy." (PMID 35073859, 2022). "The association of persistence of CAR-T cells in aggressive lymphoma is still debatable, as autologous CAR-T with CD28 signaling domain (axi-cel) with shorter persistence can still ensue durable responses in aggressive lymphomas." (PMID 35212892, 2022). "The generated CAR-NK-92 cells targeting CD19 and/or CD138 antigens that employ CD28, 4-1BB, and CD3ζ signaling displayed high and selective cytotoxicity against established leukemia, lymphoma, and MM cells in vitro." (PMID 34337077, 2021). "In this article, we show that inactivation of GSK-3α/β through siRNA or by SMIs during priming can substitute CD28 co-stimulation in the potentiation of cytotoxic CD8+ CTL function against the EL-4 lymphoma cells expressing OVA peptide." (PMID 29312284, 2017). "Our hypothesis was that the need for durable CAR-T cells in these diseases is limited, and that CD28 costimulation may overcome the aggressive nature of these lymphomas." (PMID 40269280, 2025). "Consistent with the effects of PD-1 in inhibiting TCR signaling and also CD28 co-stimulation, PD-1 inhibition mildly increased Card11M365K/M365K CD4 T cell accumulation in vivo, but was nevertheless insufficient to cause CD4 lymphoma or lymphoproliferation." (PMID 36960072, 2023).
lymphoma (continued). "Vav1 deficient patients and Vav1 loss of function lymphomas murine models of lymphomas show defects in F-actin accumulation, F-actin reorganization in response to TCR/CD28 co-engagement and the impairment in both positive and negative selection of T cells in the thymus." (PMID 33928032, 2021). "The PD1-CD28 CAR containing extracellular domain of PD1 fused to the intracellular co-stimulatory CD28 could also render the higher antitumor activity against PDLI+ lymphoma cells." (PMID 38993780, 2024). "Besides inducing T-cell anergy and, thus, fostering immune escape, CTLA4 has also a direct oncogenic effect: a fusion of the two opponents CTLA4 and CD28 has recently been described in a variety of T-cell lymphomas and proposed to be a major driver of lymphoma development." (PMID 29564225, 2018). "We had only two CVID cases with lymphoma and we could not find any relationship between lymphoma formation and percentage of CD28-deficient NK cells." (PMID 25964782, 2015). "The commonly used costimulatory domains are CD28 and/or 4-1BB (CD137), and the second generation CARs targeting CD19 showed remarkable and durable efficacy in patients with lymphoma and leukemia of B cell origin." (PMID 40045373, 2025). "The combination of CD27 and CD28 costimulatory domains in a 3rd-generation CAR produced encouraging clinical results in neuroblastoma, AML, and lymphoma patients." (PMID 36123710, 2022). "Researchers constructed three types of CD19-CAR NK-92 cells for the study of B-cell leukemia and lymphoma, including NK-92/63.z cells (1st generation CAR), NK-92/63.28.z cells (2nd CAR, CD28) and NK-92/63.137.z cells (2nd CAR, CD137)." (PMID 36032149, 2022). "The selected studies focused on lymphoma patients treated with CAR-T cell targeting CD19, and we explored the different effects of co-stimulatory molecule (CD28 vs. 41BB) with the extracted data." (PMID 35073859, 2022). "Clinically, the CD27/CD28 co-stimulatory combination yielded impressive responses in neuroblastoma, AML, and lymphoma patients." (PMID 35053463, 2022). "We next examined the T cell capacity to kill A20 lymphoma cells, coated with anti-CD3 and anti-CD28 antibodies, by live cell imaging." (PMID 33621210, 2021). "In CD30-targeting CAR-T cells, CD28 and OX40 costimulatory combination promotes antitumor efficacy and improves persistence and proliferation in vivo against CD30+ lymphoma." (PMID 33150182, 2020). "Combination of CD28 and 4-1BB domains in CD19 CAR-T cells showed more robust expansion and longer persistence than CD28 only in patients with lymphoma." (PMID 33150182, 2020). "We elucidate the pathophysiological role of immunosuppressive networks in lymphomas, ranging from changes in the cellular microenvironment composition to distinct signaling pathways such as PD1/PDL1 or CTLA4/B7/CD28." (PMID 29564225, 2018). "Supernatants of ocular cells were harvested from 24 eyes with lymphoma and stimulated by beads coated with anti-CD3 and anti-CD28 monoclonal antibodies: they contained from 6.7 to 1204 pg/ml of IL-17 (mean: 239 pg/ml)." (PMID 21949734, 2011). "Compared to conventional T-CAR that is driven by CD28 and CD3ζ signaling domains, this NK-tailored CAR produced a more potent antitumor cytotoxic activity in NK cells, both in vitro and in vivo, in a model of CD19-expressing lymphoma." (PMID 40045373, 2025). "The results from anti-CD19 CAR T cell therapy with CD28 showed that permanent persistence of CAR T cells is not required for the maintenance of remission in patients with lymphoma." (PMID 34272481, 2022).
lymphoma (continued). "Ratio of NK cells (p: 0.401), CD28+ NK (p: 0.915), or CD28− NK (p: 0.944) cells did not effect the presence of lymphoma." (PMID 25964782, 2015). "In addition to frequent somatic mutations in RHOA and epigenetic modifiers, several studies have shown frequent alterations affecting TCR signaling-related genes, including CD28, FYN, PLCγ1 and VAV1 in cutaneous T-cell lymphomas, AITL and adult T cell leukemia/lymphoma." (PMID 30814910, 2019). "Interestingly, treatment with CD19-28BBζ prolonged the survival of lymphoma-bearing mice to a greater extent than treatment with CD19-BBζ CAR T cells, indicating that 4-1BB molecule enhances the co-stimulatory properties of the CD28 molecule in umbilical cord blood T cells." (PMID 28496440, 2017). "We corroborated the gene expression data by monitoring the expression of several activation markers, including CD25, CD40L, HLA-DR, CD28, CD38, CD44 and CD69, showing no significant modulation when CAR.CD19-T cells are stimulated by the lymphoma DAUDI cells in the presence of INFγ neutralization." (PMID 37296093, 2023). "Alternatively, due to the inherent ability of lymphomas to replicate without external signals, the activation of the T cell receptor via CD3/CD28 may not ‘stimulate’ the cells in the same manner as primary cells." (PMID 35087510, 2021). "Pre-clinical data showed that CD28 co-stimulation and co-expression of IL-15 yielded the best CAR cell durability, relocation to tumor sites, and tumor control in murine neuroblastoma and lymphoma models, while inducing no symptoms of GvHD." (PMID 32429316, 2020).
myeloma (46 papers, 2012 to 2025). "Aberrant expression of CD28 has been observed on multiple myeloma cells, is associated with disease progression, and can be associated with a poor prognosis." (PMID 38786100, 2024). "The loss of CD28 expression is a sign of T cell aging in healthy individuals, and we found it further enhanced in myeloma patients." (PMID 27809856, 2016). "Additionally, the aberrant expression of CD28 on myeloma cells is associated with the progression to stroma-independent disease." (PMID 38786100, 2024). "For instance, blocking CD28 interactions using a CTLA-4 monoclonal antibody (mAb) could prevent the immune escape of myeloma cells and make them more susceptible to CD8+ T cells." (PMID 33562441, 2021). "SAR442257 showed greater multiple myeloma cell cytotoxicity than the typical bispecific null-mutant CD28 antibody." (PMID 38421887, 2024). "We found that CD28 is expressed in a significant proportion of myeloma cells, particularly in relapsed/refractory disease." (PMID 38786100, 2024). "We quantified CD28 expression in myeloma cell lines and patient samples, including newly diagnosed and relapsed/refractory cases." (PMID 38786100, 2024). "This is of major importance, especially since the frequency of CD28 expression is increased during myeloma progression." (PMID 38786100, 2024). "One such agent, SAR442257, is a trispecific TCE that binds CD38 on multiple myeloma cells, CD3 on T cells and CD28, which is expressed on T cells and some multiple myeloma cells." (PMID 38421887, 2024). "Activation of CD28 on multiple myeloma (MM) plasma cells, by binding to CD80 and CD86 on dendritic cells, decreases proteasome subunit expression in the tumor cells and thereby helps them evade being killed by CD8+ T cells." (PMID 38654298, 2024). "This study investigates the molecular pathway downstream of CD28 activation, using an in vitro model consisting of myeloma cell lines stimulated with anti-CD28-coated beads." (PMID 38654298, 2024). "Myeloma cells interact with surrounding immune cells via CD28 and programmed cell death 1 ligand 1 (PD-L1) molecules." (PMID 35692781, 2022). "Plasma and myeloma cells express CD28, a protein known for its role in providing co-stimulatory signals required for T cell activation and survival." (PMID 35692781, 2022). "The costimulatory signal by CD28 not only promotes cytotoxic T cell activation and proliferation, but the binding of TrisAb to CD28 on myeloma cells also increases the affinity of Ab to tumor cells, which leads to reveal higher cytotoxic potential." (PMID 34072645, 2021). "In the case of myeloma, it has been shown that endogenous CD28 expressed on myeloma cells increases the production of IL-8 in MM patients." (PMID 33808304, 2021). "Plasma and myeloma cells are dependent on CD28 signaling through both the PI3K and Vav signaling pathways." (PMID 33634031, 2020). "Plasma and myeloma cells also express CD28, a transmembrane protein classically known for its role in T cell co-stimulation." (PMID 33634031, 2020). "In untreated myeloma patients, CD28 expression was significantly altered compared to healthy individuals, but only in CD8+ T-cells, which is a known phenomenon in myeloma patients." (PMID 33363008, 2020). "CD86, which is the cognate ligand for the prototypic T cell co-stimulatory molecule CD28, is expressed by myeloma cells and is required for their survival." (PMID 32751699, 2020). "CD28 is also expressed on the malignant BM-resident PC in multiple myeloma (MM) and normal PC, but its function in B lineage has not been well characterized." (PMID 32751699, 2020). "A mechanism for myeloma autocrine pro-survival loop lies in the co-expression of CD28 and its ligand CD86." (PMID 33634031, 2020). "Pre-stimulation ex vivo of allogeneic T cells by exposure to MOPC315.BM MM cells in the presence of IL-2, anti-CD3 and anti-CD28 resulted in expansion of the myeloma-reactive T cell TCRVβ 2, 3 and 8.3 subfamilies." (PMID 31727148, 2019).